ATM (ATM serine/threonine kinase)
Diseases named in the same sentence as ATM in open-access papers (continued):
Sharing a sentence is not in itself a finding about the gene and the disease.
tumor (continued). "ATM under expression was significantly correlated with tumor stage, vascular invasion, and malignant behavior." (PMID 31286981, 2019). "Meanwhile p-ATM, p-p65 and Bcl-xl also showed an elevated expression in HCCs compared with non-tumor hepatic tissues, which is consistent with in vitro experiments." (PMID 31754340, 2019). "Studies have shown that hyperactivation of ATM promotes tumor progression, metastasis, and drug resistance." (PMID 31783569, 2019). "As siRNA is not yet a reliable method for treatment in vivo, therefore we next tested the effect of combined antagonism of full-length AR plus inhibition of ATM on CRPC tumor growth in vivo." (PMID 31083651, 2019). "Combination of olaparib with a lower dose of AZD7648 (37.5 mg kg−1 bid × 53 days) in FaDu ATM KO xenografts also induced effective tumour regression, albeit with a delay compared with the higher dose." (PMID 31699977, 2019). "The ATR/ATM pathway is crucial for the survival of tumor cells in responding to DNA replication stress and DNA damage." (PMID 31803607, 2019). "Potentially actionable mutations detected from initial IDHWT tumours included EGFR, PTEN, BRCA1, BRCA2, ATM, and ATR." (PMID 32082376, 2019). "Indirectly, inhibition of the TGFβ-signaling or mitogen-activated protein kinase (MAPK) pathway can lead to reduced ATM activation and increased tumor cell radiosensitivity through reduced DSB repair." (PMID 31649878, 2019). "To determine the mechanisms by which ATM promotes tumor metastasis, we performed the IHC staining using xenografts tumor tissues obtained from A549P cell –injected and A549cisR cell-injected mice treated with CP466722 or vehicle." (PMID 30961670, 2019). "At the transcriptomic level, tumours with high MYC mRNA and low ATM mRNA expressions had increased tumour size, ER− and PR− tumours (all adjusted p values ≤ 0.01)." (PMID 30746633, 2019). "ATM is a well‐known tumour suppressor playing important roles in DNA damage repair and in responses to oxidative stress." (PMID 31565865, 2019). "As observed with cytokine secretion, irradiation-induced ATM phosphorylation increased the migration of PBMCs, which was blocked by treatment of the tumor cells with an ATM inhibitor." (PMID 29615613, 2018). "We found that LOH at the ATM locus was more frequent in tumours from HetAT subjects (67%) than in ‘sporadic’ tumours from TCGA (40%) and from previous studies investigating LOH in tumours from sporadic BC cases (20–40%)." (PMID 29665859, 2018). "Activation of Ataxia telangiectasia mutated (ATM) and ATM- and Rad3 (ATR)-related protein kinases is implicated in CD155 upregulation in tumor cells." (PMID 30039180, 2018). "Genetic inactivation of Beclin-1, an autophagy regulator, significantly reverses mitochondrial abnormalities and tumor development in ATM-null mice, independently of DDR." (PMID 29616191, 2018).
tumor (continued). "Unexpectedly, allelic loss of the autophagy regulator Beclin-1, significantly delayed tumor development in ATM-null mice." (PMID 29616191, 2018). "For example ATM, one of the recently reported potential SBA driver genes, was ranked the 10th most significant gene in our MSS tumor set, with half of the mutations being truncating." (PMID 29522538, 2018). "Both the ATM and CHEK2 genes showed significantly higher mutation rates in patients with non‐TNBC versus patients with a TNBC tumor phenotype (ATM: 1.7% vs. 0.4%; P = .026; CHEK2: 3.3% vs. 0.8%, P = .002)." (PMID 29522266, 2018). "Our results are consistent with recently published results on tumour-derived genome sequences from seven BCs from TCGA carrying an ATM TV." (PMID 29665859, 2018). "Transfected tumor cells were analyzed for the expression of p-ATM expression after culture for 24 h using the FACS analysis." (PMID 29625565, 2018). "To extend the repertoire of somatic alterations in ATM-associated tumours, we performed WGS on the four frozen tumours available." (PMID 29665859, 2018). "ATM is also involved in the early steps of EBV latency establishment where it plays a tumor suppressor role." (PMID 30662441, 2018). "In both mouse and human non-tumor cells, genotoxic stress and inhibition of DNA replication via the DNA damage pathway through ATM or ATR protein kinases, leads to increased surface expression of NKG2D-ligands." (PMID 29973929, 2018). "Altogether these results suggest that ATM restoration is theoretically a viable option for A-T patients; however, further studies are necessary to dissect the timing for tumor onset prevention or regression after tamoxifen treatment." (PMID 29472706, 2018). "Metformin activates the DNA damage reparation pathway via ataxia telangiectasia mutated (ATM) activation, which inhibits tumor growth." (PMID 30186236, 2018). "Loss/LOH was confirmed by whole-genome analysis for loci 8p21.3, 11q21-q24.2 (containing ATM), 13q13.3-q32.3, 16q22.1 and 17p13.3, whereas discordant results were obtained at locus 21p11.2-p11.1 for one tumour and at locus 22p11.23 for two tumours." (PMID 29665859, 2018). "Different DDR inhibitors, including ATM inhibitors, have been administered in combination with doxorubicin and other drugs to sensitize tumor cells to doxorubicin-induced OS and DNA damage." (PMID 29770165, 2018). "In response to elevated ROS, ATM activates the TSC2 tumor suppressor through the LKB1/AMPK metabolic pathway in the cytoplasm to repress mTORC1 and induce autophagy." (PMID 29770165, 2018). "ATM is mainly involved in the recruitment of DNA repair complexes in response to single or double strand breaks, hence the relationship between AT and neoplasms." (PMID 30839777, 2018). "Among them, ATM (associated with DNA repair) and HIF‐1α (associated with hypoxia in tumor microenvironment) are possibly correlated with radiosensitivity in A549 cells and CD133+ stem‐like cells." (PMID 29860718, 2018). "Both malignant cell-specific ATM expression and the ratio of ATM expression within malignant tumour cells compared to that in the surrounding tumour stroma, defined as the ATM expression index (ATM-EI), were measured and correlated with clinical outcome." (PMID 28418844, 2017). "Our results in the human tumor tissues are thus consistent with our earlier observations that spDSB-induced ATM activation leads to a more aggressive tumor phenotype." (PMID 28337983, 2017). "We then examined the relationship in GBM patient tumor samples between ATM expression and survival or severity of disease." (PMID 29348882, 2017).
tumor (continued). "NSG mice were injected subcutaneously with MT330 GBM cells and after 2 weeks of tumor formation mice were treated with the pharmacological ATM inhibitor KU55933." (PMID 29348882, 2017). "In line with our in vitro findings, CUR significantly increased p-ATM expression in the transplanted tumor burdens." (PMID 28881600, 2017). "In the phosphatidylinositol kinase-related family, ATM consists of many conserved domains and is a tumor suppressor." (PMID 29238697, 2017). "In contrast, knock down of mTOR enhanced cell death in tumor cells transfected to knock down the expression of AMPK, and to a lesser extent than that caused by ATM knock down." (PMID 27903966, 2017). "Now that we have established spDSB-activated ATM/ATR to be important for sustaining tumor growth, the next logical question is which downstream factors of ATM are responsible for supporting tumorigenicity." (PMID 28337983, 2017). "After only one week, inhibiting ATM activity by KU55933 treatment markedly suppressed tumor growth of MT330 GBM cells." (PMID 29348882, 2017). "Patients with low ATM-EI tumours had worse survival outcomes compared to those with high ATM-EI (p < 0.01)." (PMID 28418844, 2017). "ATM is a tumor suppressor gene that belongs to the family of proteins that respond to DNA damage by phosphorylating key substrates involved in DNA repair and/or cell cycle control." (PMID 29113313, 2017). "High ATM-expressing tumours, similar to normal lung tissue, had a strong distinct nuclear expression pattern in both malignant epithelial and stromal cells." (PMID 28418844, 2017). "Pharmacologic inhibition of tumor cell growth was ATM-dependent and was mediated through mitotic catastrophe, independently of apoptosis." (PMID 29262669, 2017). "In summary, our findings suggest that low miRNA203a expression in GBM suppresses the IFN response by an ATM-dependent pathway, and that miR-203a has tumor suppressive function in GBM by inhibiting the pro-tumorigenic function of ATM." (PMID 29348882, 2017). "In some of the patient-derived tumor samples from both cohorts, there was widespread activation of ATM as demonstrated by strong nuclear pATM staining." (PMID 28337983, 2017). "In summary, our study determined that the main tumor suppressor role of ATM in the pancreas is to maintain genomic stability." (PMID 28894253, 2017). "By using the digital image analysis capability of the HistoRx AQUA® platform, we were able to quantify ATM protein levels and to define the specific localization of ATM expression within the tumour." (PMID 28418844, 2017). "The observation that ATR and ATM inhibitors have different effects on DDR in monolayer cells compared to MCTS highlights the importance of recreating a 3D tumor environment when validating therapeutic targets." (PMID 28521819, 2017).
tumor (continued). "The inhibitory effect on tumor formation and increase in animal survival upon ATM-KO and/or pharmacologic inhibition of ATM function mirrored what we observed upon enforced miR-203a expression and was consistent with our previous findings." (PMID 29348882, 2017). "Given the importance of ATM as a master regulator in the cell ensuring DNA replication fidelity, it makes ATM an attractive target to enhance the sensitivity of tumor cells to DNA damaging chemotherapeutic agents and radiation." (PMID 29340025, 2017). "We further observed that HS-173 inhibited tumor growth by enhancing the efficacy of radiation through inhibition of elements of the DNA damage repair response pathway, including ATM and DNA-PKcs." (PMID 29348875, 2017). "Using ROC-AUC analysis of good versus poor histological tumor response among patients treated preoperatively with radiotherapy, the average ROC-AUC was 0.745 for the combined panel, 0.618 for ATM alone, and 0.711 for MRE11 alone." (PMID 27930716, 2016). "Increased methylation at 11 ATM promoter region probes proximal to the TSS in the tumor-derived DNA (Δβ 3.25%; adj." (PMID 27902704, 2016). "Associations between the combined expression of ATM and MRE11 in the tumor center and tumor periphery and clinicohistopathological data." (PMID 27930716, 2016). "This indicates that MEK inhibition in ATM-depleted tumours in vivo elicits a combination of proliferation arrest and apoptosis resulting in a strong inhibition of tumour growth." (PMID 27922010, 2016). "ATM, ATR, Chk1, Chk2 have been identified as candidate multi-organ tumor suppressor genes and their mutations lead to oncogenic transformations." (PMID 27442013, 2016). "The distribution of ATM staining in tumor cores tends to follow a bi-modal distribution with clear distinction between “positive” and “negative” staining cores." (PMID 27259260, 2016). "Our data demonstrating the importance of p27Kip1 in the establishment of a G1 checkpoint arrest downstream of ATM uncovers another layer to its tumor suppressing functions." (PMID 27611996, 2016). "Specifically, ATM wild-type tumours increased in size almost sevenfold over the course of the 33-day experiment." (PMID 27922010, 2016). "ATM expression was higher in normal mucosa taken near the tumor (M = 6.43) compared to samples taken away from the tumor (M = 4.25)." (PMID 27930716, 2016). "If any of 2 or more cores stained positive for ATM in tumor cell nuclei that case was scored as positive." (PMID 27259260, 2016). "miR-421 has also been described as negatively regulating ATM expression, leading to clinically manifest tumor radiosensitivity." (PMID 27973455, 2016). "ATM (Ataxia telangiectasia mutated) is a serine/threonine protein kinase, a key DDR kinase and tumor suppressor, that is recruited and activated by DSBs induced by ionizing radiation or genotoxicity drugs." (PMID 27258253, 2016). "Although ATM is considered to be a tumor suppressor, up-regulation of ATM signaling promotes chemoresistance, radioresistance and metastasis." (PMID 26901759, 2016). "In contrast ATM null tumours markedly slowed down growth the first week upon commencing drug treatment and subsequently tumour volume remained stable until the end of the experiment." (PMID 27922010, 2016). "Our data provide a novel aspect of the tumor suppressing functions for p27Kip1 where it directly participates in the G1 DNA damage signaling cascade downstream of ATM." (PMID 27611996, 2016). "A second potential therapeutic approach for ATM-defective human neoplastic disease has recently emerged from preclinical model systems." (PMID 26113859, 2015).
tumor (continued). "ATM, which expresses in a variety of tumor, is commonly considered as a tumor suppressor for its role in DNA damage repair machinery and in SATB1-induced tumorigenic progression." (PMID 26528698, 2015). "Our study emphasizes the ability of ATM to regulate the transcription of a sub-set of genes involved in tumor promoting pathways." (PMID 26030852, 2015). "There, we observed an increase in primary tumor growth, consistent with the well-established role of ATM in tumor suppression." (PMID 26030852, 2015). "In transplanted B16 melanomas, ROS led to the activation of endothelial ATM, which specifically resulted in tumor angiogenesis." (PMID 26000250, 2015). "In the tumor DNA of the germline ATM p.R23X (c.67G > T) carrier in the TCGA dataset, a somatic frameshift insertion in ATM (c.1024dupA, p.V341fs) was reported." (PMID 26506520, 2015). "Up-regulating miR-101 efficiently reduced the protein levels of DNA-PKcs and ATM in these tumour cells and most importantly, sensitized the tumour cells to radiation in vitro and in vivo by targeting DNA-PKcs and ATM." (PMID 26238857, 2015). "To examine the influence of ATM on tumor growth in vivo, we then orthotopically injected these cells into the mammary fat pad." (PMID 26030852, 2015). "The level of ATM gene expression was significantly upregulated in 50% of day21group and 100% of day33 group, which signifies the mechanism behind the tumor suppression." (PMID 26176230, 2015). "Case M115 had the nonsense mutation in exon 39 (p.R1882X) as well as LOH for marker D11S1818, suggesting that ATM function was abolished in this tumor." (PMID 25625042, 2015). "Here, ATR and ATM indeed cooperated in their response to chemotherapeutics in different tumor contexts." (PMID 26208482, 2015). "Using a dCK specific PET probe, we visualized and quantified IR-induced ATM-dependent activation of the dN salvage pathway, manifested as an increased probe accumulation in the tumor 1 hour after tumor irradiation." (PMID 25101980, 2014). "135/186 (72.6%) tumours were low for ATM expression and 51/186 (27.4%) of the tumours were high for ATM expression." (PMID 26674120, 2014). "We observed that inhibition of the cAMP in tumor cells by 7-ddA, H89, or the combination, significantly suppressed the phosphorylation of ATM in tumor-treated T cells." (PMID 25231413, 2014). "We found that [18F]-FAC PET is effective in measuring acute tumor responses to IR, indicating potential clinical utility of this imaging modality in assessing the ATM-mediated DNA damage response in vivo." (PMID 25101980, 2014). "Taken together, ATM +/DNA-PKcs +/ATR + tumours had the worst survival compared to ATM-/DNA-PK-/ATR- tumours." (PMID 26674120, 2014). "In human clinical samples, loss of ATM expression correlated with higher ARF protein levels and in xenograft experiments inhibition of ATM promotes the tumor-suppressive function of ARF." (PMID 24681585, 2014). "Evidence for a role of ATM in tumor initiation and progression comes also from studies aimed at the generation of mouse models in which ATM activity has been genetically modulated." (PMID 24681585, 2014). "In particular, by assigning an ATM mutation similar probability of belonging to the founding clone and a subclone, SciClone reflected the lack of certainty inherent in the data and indicated that their sparsity may poorly characterize the tumor's clonal diversity." (PMID 25102416, 2014). "The early-identified tumor suppressor MiR-16 also regulates ATM signaling indirectly, through targeting the ATM inhibitor WIP1." (PMID 25141103, 2014).